DES (desmin)
Diseases named in the same sentence as DES in open-access papers (continued):
Sharing a sentence is not in itself a finding about the gene and the disease.
desminopathies (continued). "Here we showed that coxsackievirus infection induced desminopathy-like phenotype of the myocardium, as characterized by the accumulation of protein aggregates and the disruption of desmin organization." (PMID 29088822, 2017). "Desminopathies are classical protagonists of a clinically and genetically diverse group of myofibrillar myopathies; which are morphologically characterized by desmin-positive protein aggregates and myofibrillar degeneration." (PMID 28469177, 2017). "A major histopathological feature of desminopathy is the accumulation of insoluble desmin and partner proteins including CRYAB into aggregates." (PMID 28470624, 2017). "Our combined morphological-biomechanical investigation unveils early, pre-clinical desminopathy disease patterns where mutant desmin disrupts the extra-sarcomeric intermediate filament network, causing aberrant myofibrillar alignment and orientation." (PMID 28469177, 2017). "CRYAB is a major component in the desmin aggregates taken from muscle biopsies of patients with desminopathies." (PMID 28470624, 2017). "The desmin aggregation displayed typically in the desminopathy-like muscle fibers by immunohistochemistry." (PMID 27941998, 2016). "This pathological analysis presents the correlation between VDAC1 and desmin, and apoptosis related proteins are correlated in the desminopathy." (PMID 27941998, 2016). "Immunofluorescence results showed that VDAC1 was accumulated in the desmin highly stained area of muscle fibers of desminopathy patients or desminopathy rat model compared to the normal ones." (PMID 27941998, 2016). "Lastly, we studied the mtDNA copy numbers in the same skeletal muscle tissue specimens derived from the human desminopathy patients as well as the R349P desmin knock-in and desmin knock-out mice." (PMID 27393313, 2016). "We have found that ATF2 deposited in the skeletal muscle fibers with desmin deposition of desminopathy patients and animal models, which suggests that desmin deposition in muscle fibers and tends to apoptosis." (PMID 27941998, 2016). "In this study, we investigated the relationship between mutant desmin and mitochondrial pathology by comprehensive and multi-level analyses in human and murine desminopathies." (PMID 27393313, 2016). "A marked reduction of the mtDNA copy number was observed in the aged R350P desminopathy patient with the multiple mtDNA deletions, and in homozygous desmin knock-in and homozygous desmin knock-out mice." (PMID 27393313, 2016). "For the first time, we report the expression level and subcellular distribution of mutant versus wild-type desmin in our mouse model as well as in skeletal muscle specimens derived from human R350P desminopathies." (PMID 25394388, 2015). "Our knock-in mouse strain represents the first physiological animal model for autosomal dominant and recessive human desminopathies, as the expression of the mutant desmin is controlled by the endogenous gene regulation sites." (PMID 25394388, 2015). "Seeking to inhibit desmin aggregation by stimulating cellular defenses against protein aggregation to identify possible therapies for desminopathies, we screened several approaches to activate anti-aggregative cellular mechanisms." (PMID 26333167, 2015). "Desminopathies are morphologically characterized by sarcoplasmic and subsarcolemmal desmin-positive protein aggregates and degenerative changes of the myofibrillar apparatus." (PMID 25394388, 2015). "In contrast to both previously published transgenic desminopathy mouse models, our knock-in approach has the striking advantage that the expression of the mutant desmin gene remains under control of the endogenous gene regulation sites." (PMID 25394388, 2015). "Information on the expression, localization, interaction, and function of IFs in general and desmin in particular is a prerequisite for the understanding of human desminopathies." (PMID 23143191, 2013).
desminopathies (continued). "Desmin-positive protein aggregates in desminopathies also show a positive immunoreactivity with antibodies directed against HspB1 (synonyms: Hsp25, Hsp27) and HspB5 (synonym: αB-crystallin)." (PMID 23143191, 2013). "To obtain a cell model more closely resembling expression in desminopathies, with a mutant/WT desmin expression ratio of around 1:1, we established doxycycline inducible, stable cell clones expressing Myc-tagged desmin." (PMID 24098483, 2013). "Beyond specific desmin modifications, skeletal muscle samples from desminopathies exhibited increased levels of glycoxidated, lipoxidated, and nitrated proteins." (PMID 23143191, 2013). "In the present article we will summarize the essential data on desmin and desminopathies derived from numerous clinical and molecular studies." (PMID 23143191, 2013). "Other studies have demonstrated increased levels of the glycoxidation markers AGE, CML, and CEL in muscle samples from individuals with desminopathies, and desmin has been identified as a major target of oxidation and nitration." (PMID 24098483, 2013). "Another study demonstrated an enrichment and co-localization of the mutant ubiquitin UBB+1 as well as the autophagy-related p62 with desmin-positive protein aggregates in desminopathies." (PMID 23143191, 2013). "Together with previous studies on secondary mitochondrial dysfunction in desminopathies, [S38], our new results provide a more detailed insight into the mutant desmin‐induced down‐regulation of mitochondria‐related key candidates promoting metabolic dysregulation in skeletal muscle tissue." (PMID 41165044, 2025). "In the absence of TANGO2, reduced levels of desmin lead to desminopathy in mice and in patient cells with a TANGO2 mutation." (PMID 40480980, 2025). "While a direct role for desmin IFs in autophagic transport has not yet been established, desmin deficiency as well as desminopathy‐causing mutations lead to imbalanced protein homeostasis in murine muscles." (PMID 40641151, 2025). "Considering that desmin degradation appears to be the trigger for muscle wasting, strategies aimed at preventing desmin degradation are being explored as therapeutic approaches for desminopathies and muscle atrophy." (PMID 37760006, 2023). "Indeed, muscle proteins from patients with desminopathies show features of oxidation and aggregation, and desmin itself has been shown to be oxidized and nitrated in affected muscles in myotilinopathies and desminopathies." (PMID 37760006, 2023). "Moreover, we know that the desmin-rich aggregates found in patients with desminopathies are composed of several proteins captured during their formation." (PMID 35350386, 2022). "In the very rare recessive desminopathies, a subset of DES mutations leads to desmin deficiency." (PMID 36233322, 2022). "In the whole heart specimens from the SU/Hx animals, we also saw a striated staining pattern for desmin and troponin-I, however, it was frequently irregular, and in addition, we detected areas with deposition of desmin aggregates, as is observed in desminopathies." (PMID 36142826, 2022). "Disruption of the link between STIM1 and desmin may alter STIM1-Ca2+ signaling and contribute to the muscle degeneration and weakness associated with desminopathies." (PMID 34494555, 2021). "Consequences of desmin alterations are well-described in the context of desminopathies." (PMID 33875675, 2021). "Similarly, in the recessive desminopathy mouse model with low expression of the mutant R349P desmin protein, the same authors demonstrated neuromuscular endplate pathology." (PMID 33923914, 2021). "Desmin-positive protein aggregates correlate with high levels of ATF2, voltage-dependent anion-selective channel protein 1 (VDAC1), and BCL2 Associated X (BAX) in muscle fibers of desminopathy patients." (PMID 34272480, 2021). "For desminopathies, there is an experimental study aim to reduce desmin aggregation." (PMID 35068951, 2021).
desminopathies (continued). "Several findings obtained in laminopathic or desminopathic muscle suggest that a functional interplay of desmin and lamin A/C disrupted under pathological conditions may contribute to the pathogenesis of both muscular laminopathies and desminopathy." (PMID 33923914, 2021). "Consequently, the main histopathological hallmarks of desminopathy are sarcoplasmic and subsarcolemmal desmin‐positive protein aggregates." (PMID 32893996, 2020). "While there are a number of murine models of desmin mutations available, no rat model for desminopathy had been developed." (PMID 32893996, 2020). "Desminopathies comprise a heterogeneous group of inherited and sporadic myopathies which, in most cases, share a common morphological picture comprising sarcoplasmic and subsarcolemmal desmin-positive protein aggregates and signs of myofibrillar degeneration." (PMID 32752098, 2020). "In the R349P desminopathy model, we likewise observed that the lacking functional desmin causes a stiffening in mutant fibers." (PMID 32752098, 2020). "VDAC1 is involved in desmin aggregation in the patients with desminopathy." (PMID 27941998, 2016). "To address putative mtDNA damage, we performed long-range PCRs using DNA extracted from skeletal muscles derived from three human desminopathy patients as well as from 6-month-old wild-type, heterozygous and homozygous littermates of our R349P desmin knock-in mice." (PMID 27393313, 2016). "Furthermore, we provide a rat model of desminopathy for the investigation of desmin related myopathy." (PMID 27941998, 2016). "The last 2 decades have led to a number of important insights into the molecular pathogenesis of desminopathies, but the precise and sequential molecular mechanisms leading from mutant desmin to consecutive pathological protein aggregation and progressive muscle damage still remain to be elucidated." (PMID 23143191, 2013). "Mutations in the gene encoding desmin (DES, HGNC: 2770) are responsible for the most studied subgroup of myofibrillar myopathies (MFM), diseases affecting cardiac and skeletal muscles, called desminopathies." (PMID 24098483, 2013). "However, desminopathies highlight other potential important roles of desmin." (PMID 35350386, 2022). "Importantly, cardiomyocyte death due to the mitochondrial defects caused by the absence of desmin triggers an inflammatory condition involving complement activation and macrophage infiltration in desminopathy preclinical models." (PMID 33923914, 2021). "Thus, mitochondrial defects caused by absence of a functional desmin network are a key pathogenetic factor in desminopathy." (PMID 33923914, 2021). "As secondary inflammatory processes and cytokine secretion may also affect desmin structure and localization at intercalated disks, as shown upon TNF-α-induced caspase cleavage of desmin in heart failure models, anti-inflammatory treatments could be also suggested in desminopathy." (PMID 33923914, 2021). "The results in our three desminopathy models, i.e., heterozygous and homozygous desmin knock-in and homozygous desmin knock-out mice, indicate that the expression of mutant desmin rather than the lack of desmin cause the mtDNA instability." (PMID 27393313, 2016). "Thus, we generated a R349P desmin knock-in mouse model for human desminopathies." (PMID 25394388, 2015). "The PRM results were consistent with the relative quantification results obtained by label-free analysis, and validated the finding that desmin and FLNC are over-represented in desminopathy aggregates." (PMID 26633379, 2015). "The relative expression of desmin and filamin C (FLNC) peptides, obtained from skeletal muscle samples from desminopathy patients, was validated using PRM." (PMID 26633379, 2015).
desminopathies (continued). "Furthermore, the mere expression of various desmin mutants impacts autophagic flux in C2C12 myoblasts and desminopathy patients with autophagic vacuolar myopathies have been reported." (PMID 40641151, 2025). "For comparison, we used the W2711X filamin‐C knock‐in mice as well as desmin knock‐out mice, a model for the rare autosomal recessive desminopathy subform without desmin expression, and corresponding wild‐type siblings." (PMID 40947309, 2025). "In particular, N-acetyl-cysteine has been reported to prevent oxidative stress-induced desmin aggregation in cellular models of desminopathy, and tocopherols decreased the proportion of C2C12 myoblasts displaying spontaneous aggregates upon transfection of a GFP-Desmin D399Y mutant." (PMID 37760006, 2023). "Further insights into the pathogenesis of desminopathies and, by extension, desmin-related ACM, have been made possible through the development of a knockout DES murine model, which many laboratories have used to recapitulate desmin-related CMP phenotypes." (PMID 37895213, 2023). "Human desminopathies with a lack of desmin protein are very rare and, to our knowledge, no published data on acylcarnitines and amino acid blood levels are currently available." (PMID 36233322, 2022). "An absence of desmin aggregates has been recently documented both in autosomal dominant and autosomal recessive desminopathy." (PMID 32235386, 2020). "As a model for the autosomal-recessive desminopathy patients lacking desmin protein expression we employed DKO mice, which display a marked cardiac phenotype." (PMID 32322014, 2019). "Future studies in mouse models of desmin aggregation and propagation will have to determine whether EGCG is a promising model compound for desminopathy in vivo." (PMID 31371504, 2019). "The very few thus far reported human patients suffering from a desminopathy due to a complete lack of desmin protein basically all die from their severe cardiac disease manifestation." (PMID 32322014, 2019). "The virtual lack of desmin expression in the only two reported human autosomal recessive desminopathies, however, seems to be related to a different disease mechanism." (PMID 25394388, 2015). "While mouse models and human primary myoblasts have informed our understanding of desmin and desminopathies, models do not exist for all desmin mutants." (PMID 24098483, 2013). "Nonetheless, it is not clear how the information obtained from this study can be translated into the treatment of desminopathies, and these studies usually did not focus on the subcellular localization of desmin since the ‘’nuclear desmin’’ concept is relatively new." (PMID 35068951, 2021). "These mice serve as disease models for two subforms of autosomal-recessive desminopathies, the former for the one with a complete lack of desmin protein and the latter for the one with solely mutant desmin protein expression in conjunction with protein aggregation pathology in striated muscle." (PMID 32322014, 2019). "In a recent study, the analysis of citrate synthase-normalized respiratory chain enzyme activities in skeletal muscle homogenates of a heterozygous R350P desminopathy patient, who was not related to both R350P desmin patients included in this study, gave normal results." (PMID 27393313, 2016). "Meanwhile apoptosis related proteins bax and ATF2 were involved in desminopathy patients and desminopathy rat model, but not bcl-2, bcl-xl or HK2.VDAC1 and desmin are closely relevant in the tissue splices of deminopathies patients and rats with desminopathy at protein lever." (PMID 27941998, 2016). "Two-dimensional desmin gel electrophoresis in desminopathies revealed non-uniform results." (PMID 23143191, 2013).
desminopathies (continued). "Despite their usefulness as models of human disease, mouse studies have not yet extended to testing therapeutic options, except for one HSPB5-R120G cardiac MFM model without desmin primary defect, an important avenue to pursue given that no treatment is presently available for desminopathies." (PMID 24098483, 2013). "Therefore, TDD may be considered a sub-class of desminopathy and TANGO2 mutations could be screened in the clinic when patients present with a desminopathy that is not caused by desmin or CRYAB mutations." (PMID 40480980, 2025). "Notably, clinical chemistry data derived from a previously published patient (patient 2,), a case of the very rare desminopathy subform with a lack of desmin, showed blood acylcarnitine levels in a normal range, but a moderately increased C8/C10-carnitine ratio (0.980; normal range, 0.000 to 0.600)." (PMID 36233322, 2022). "Thus, our data strongly imply that total or focal disruption of the extrasarcomeric IF cytoskeleton rather than the presence of desmin protein aggregates per se is the key factor that triggers the progressive muscle fiber damage in autosomal dominant and recessive desminopathies." (PMID 25394388, 2015). "Notably, thirteen years before the first description of patients lacking desmin, two independent research groups had reported their first analyses of desmin knock-out mice, which closely mirror the human pathology of autosomal-recessive desminopathies with a lack of desmin protein." (PMID 36233322, 2022). "Though homozygous R350P desmin patients have not been described yet, our HOM mice depict essential aspects of rare autosomal recessive desminopathies due to missense, small in-frame deletion, and compound heterozygous mutations." (PMID 25394388, 2015).